HCFC1 (host cell factor C1)
Description:
Transcriptional coregulator (By similarity). Serves as a scaffold protein, bridging interactions between transcription factors, including THAP11 and ZNF143, and transcriptional coregulators. Involved in control of the cell cycle. Also antagonizes transactivation by ZBTB17 and GABP2; represses ZBTB17 activation of the p15(INK4b) promoter and inhibits its ability to recruit p300. Coactivator for EGR2 and GABP2. Tethers the chromatin modifying Set1/Ash2 histone H3 'Lys-4' methyltransferase (H3K4me) and Sin3 histone deacetylase (HDAC) complexes (involved in the activation and repression of transcription, respectively) together. Component of a THAP1/THAP3-HCFC1-OGT complex that is required for the regulation of the transcriptional activity of RRM1. As part of the NSL complex it may be involved in acetylation of nucleosomal histone H4 on several lysine residues. Recruits KMT2E/MLL5 to E2F1 responsive promoters promoting transcriptional activation and thereby facilitates G1 to S phase transition. Modulates expression of homeobox protein PDX1, perhaps acting in concert with transcription factor E2F1, thereby regulating pancreatic beta-cell growth and glucose-stimulated insulin secretion (By similarity). May negatively modulate transcriptional activity of FOXO3 (By similarity). (Microbial infection) In case of human herpes simplex virus (HSV) infection, HCFC1 forms a multiprotein-DNA complex with the viral transactivator protein VP16 and POU2F1 thereby enabling the transcription of the viral immediate early genes.
Synonyms: HCF; HCF-1; HCF1; HFC1; CFF; VCAF; MGC70925; PPP1R89; MAHCX; MRX3; XLID3
Tractability: Small molecule: a structure with a bound ligand is known. PROTAC: UniProt records ubiquitination sites on it; ubiquitination databases record sites on it; its protein half-life has been measured.
Gene: Protein-coding gene on chromosome X (153,946,434 to 153,972,427, reverse strand). Ensembl gene ENSG00000172534.
Subcellular location: Cytoplasm; Nucleus
Subcellular location (Human Protein Atlas): Nucleoplasm
Pathways (Reactome):
Chromatin organization: HATs acetylate histones
Gene expression (Transcription): Formation of WDR5-containing histone-modifying complexes
Metabolism of proteins: UCH proteinases
Organelle biogenesis and maintenance: Transcriptional activation of mitochondrial biogenesis
Gene Ontology:
Molecular function: cadherin binding; chromatin binding; DNA-binding transcription factor binding; identical protein binding; protein binding; protein-macromolecule adaptor activity; transcription coactivator activity
Biological process: positive regulation of DNA-templated transcription; positive regulation of gene expression; positive regulation of transcription by RNA polymerase II; protein stabilization; regulation of DNA-templated transcription; regulation of protein-containing complex assembly; chromatin remodeling; negative regulation of transcription by RNA polymerase II; positive regulation of cell cycle; release from viral latency
Cellular component: cytoplasm; histone acetyltransferase complex; membrane; MLL1 complex; MLL1/2 complex; neuronal cell body; NSL complex; nucleoplasm; nucleus; protein-containing complex; Set1C/COMPASS complex; histone methyltransferase complex
Gene-disease validity (ClinGen):
ClinGen rates the evidence that HCFC1 causes each of these diseases.
X-linked intellectual disability (X-linked): Definitive. An X-linked intellectual deficiency in which not enough information is known, reported or published to indicate whether a gene causes non-syndromic or syndromic presentations.
Homologues: Orthologues: chimpanzee HCFC1 (99% identical), macaque HCFC1 (96% identical), dog HCFC1 (95% identical), rabbit HCFC1 (95% identical), rat Hcfc1 (94% identical), mouse Hcfc1 (94% identical), pig HCFC1 (91% identical), tropical clawed frog hcfc1 (74% identical). Paralogues in human: HCFC2 (21% identical), FBXO42 (8% identical), LZTR1 (7% identical), KLHDC4 (6% identical), RABEPK (5% identical), KLHDC10 (5% identical), KLHDC3 (5% identical), KLHDC2 (5% identical), KLHDC1 (5% identical), KLHDC9 (3% identical).